RNU6-64P (RNA, U6 small nuclear 64, pseudogene)
Synonyms: RNU6-64
Gene: Small nuclear RNA gene on chromosome 13 (30,281,765 to 30,281,869, forward strand). Ensembl gene ENSG00000252928.
Homologues: Orthologues: chimpanzee U6 (100% identical), macaque U6 (87% identical), pig U6 (74% identical), rabbit U6 (74% identical), guinea pig U6 (72% identical), rat LOC120094407 (69% identical), guinea pig U6 (68% identical), mouse Gm25425 (67% identical), rabbit U6 (67% identical). Paralogues in human: RNU6-1316P (82% identical), RNU6-1181P (81% identical), RNU6-144P (81% identical), RNU6-38P (81% identical), RNU6-480P (81% identical), RNU6-1005P (80% identical), RNU6-1031P (80% identical), RNU6-1099P (80% identical), RNU6-16P (80% identical), RNU6-21P (80% identical), RNU6-247P (80% identical), RNU6-46P (80% identical), and 1284 more.